BMP4 (bone morphogenetic protein 4)
Diseases named in the same sentence as BMP4 in open-access papers (continued):
Sharing a sentence is not in itself a finding about the gene and the disease.
melanoma (21 papers, 2009 to 2025). A malignant, usually aggressive tumor composed of atypical, neoplastic melanocytes. "BMP4/7-dependent expression of inhibitor of differentiation/DNA binding (Id) proteins 1 and 3 has been implicated in tumor progression and poor prognosis of malignant melanoma patients." (PMID 30297743, 2018). "BMP4 is reportedly involved in human malignant melanoma and alters biological functions, and inhibits MMP9 expression in cancer cells." (PMID 38511062, 2024). "Accumulated evidence suggests that 16 genes play a tumorigenic role in several cancers; BMP4 is vital in the progression of malignant melanoma, promotes melanoma cell invasion and migration, and acts as a tumor suppressor in breast cancer." (PMID 37985782, 2023). "HA/CD44 interactions with bone morphogenetic protein (BMP) promote BMP4/7-dependent Id1/3 protein expression in melanoma, contributing to reduced survival in melanoma patients." (PMID 35154001, 2021). "Increased levels of BMP4,7/Id axis contributes to malignancy in melanoma by promoting stemness and tumor initiation." (PMID 32899370, 2020). "HA promotes BMP4/7-dependent Id1/3 protein expression in melanoma cells by binding its cellular receptor CD44 and directly aids in cell proliferation, motility, invasion and metastasis." (PMID 32899370, 2020). "In this study we found that depletion of endogenously-produced HA by hyaluronidase treatment or by inhibition of HA synthesis by 4-methylumbelliferone (4-MU) resulted in reduced BMP4/7-dependent Id1/3 protein expression in mouse melanoma B16-F10 and Ret cells." (PMID 30297743, 2018). "We therefore conclude that the CD44/HA axis can potentiate the ability of BMP4/7 to activate Id1 and Id3 expression in melanoma cells, thereby contributing to poor prognosis." (PMID 30297743, 2018). "Our results suggest that HA-CD44 interactions with BMPR promote BMP4/7-dependent Id1/3 protein expression in melanoma, contributing to reduced survival in melanoma patients." (PMID 30297743, 2018). "To analyse a potential regulation of CTGF gene expression by BMPs, we incubated Mel Im melanoma cells with recombinant BMP4, BMP7 or the BMP inhibitors noggin and chordin, respectively." (PMID 21673687, 2011). "Importantly, downregulated expression of BMP-4 in melanoma cells correlated with their diminished proangiogenic paracrine activity." (PMID 39866233, 2025). "In this study, we investigated this hypothesis, and found that the CD44/HA axis fosters BMP4/7-dependent Id1/3 protein expression in melanoma cells through interactions between CD44 and BMPR." (PMID 30297743, 2018). "Here we report that HA promotes BMP4/7-dependent Id1/3 protein expression in melanoma cells." (PMID 30297743, 2018). "To further substantiate the notion that HA promotes BMP4/7-induced Id1/Id3 expression in melanoma cells, we treated the cells with 4-MU, a 7-hydroxy-4-methylcoumarin that inhibits HA synthesis by depleting cellular UDP-glucuronic acid and downregulating HA synthase expression." (PMID 30297743, 2018). "It has been reported that BMP4 is overexpressed in melanoma cell line and lung cancer." (PMID 22537906, 2012). "Moreover, the expression of PKC-β in LH melanoma cells respond to BMP-4 similar to those found in cultured melanocytes where both the protein and the mRNA of PKC-β were reduced by treating the cells with BMP-4 (25 ng/mL) for 24 hours (data not shown)." (PMID 20130821, 2009). "Given that the CD44/HA axis promotes BMP signalling in chondrocytes, and the correlation between these factors and poor prognosis in melanoma, we hypothesized that HA might promote BMP4/7-dependent Id1/3 protein expression in melanoma cells in CD44-dependent manner." (PMID 30297743, 2018). "Using both human tumor data and mouse B16 melanoma cells, we further show that ADAM11 levels similarly correlate with Wnt or BMP4 activation levels." (PMID 37766964, 2023). "Our qPCR results showed that BMP4 was down-regulated and MMP9 was up-regulated in melanoma tissue samples." (PMID 31569419, 2019).
melanoma (continued). "Hyaluronidase pre-treatment reduced Id1/3 protein expression in response to BMP4 and BMP7 in both melanoma cell lines by around 50%." (PMID 30297743, 2018). "Moreover, two bone morphogenetic proteins (BMPs) from the TGF-β family, namely BMP-4 and BMP-7, are frequently overexpressed in melanoma." (PMID 39866233, 2025). "BMP4 is known to be regulated by LIF (leukemia inhibitory factor), which might be involved in melanoma-induced bone metastasis." (PMID 34073664, 2021). "We also determined the effect of BMP4 and BMP7 on proliferation of the melanoma cells." (PMID 30297743, 2018). "Moreover, we and others were able to determine Bone Morphogenetic Protein 4 (BMP4), BMP7 and TGFβ as important modulators of melanoma initiation and progression." (PMID 21673687, 2011). "We found that the CTGF overexpression is not induced by members of the TGFβ superfamiliy and its regulators in melanoma cell lines: Neither TGFβ1, BMP4 nor BMP7 have a significant effect on the CTGF expression." (PMID 21673687, 2011). "As TGFβ1, BMP4 and BMP7 are upregulated in melanoma, we were interested whether CTGF expression in the melanoma cells is mediated by these cytokines." (PMID 21673687, 2011). "Then, to examine whether BMP-4 suppresses the promoter activity of PKC-β, a PKC-β promoter-CAT reporter construct was transfected into paired cultures of LH melanoma cells." (PMID 20130821, 2009). "Additionally, miR-450b was overexpressed in canine melanoma metastatic cells, resulting in an increased matrix metalloproteinase-9 (MMP9) expression (which is required for tumor metastasis) and the suppression of bone morphogenetic protein-4 (BMP4)." (PMID 41227463, 2025).
endothelial dysfunction (20 papers, 2013 to 2025). In vascular diseases, endothelial dysfunction is a systemic pathological state of the endothelium (the inner lining of blood vessels) and can be broadly defined as an imbalance between vasodilating and vasoconstricting substances produced by (or acting on) the endothelium. "The bone morphogenetic protein 4 (BMP4)-ROS cycle in db/db mice causes oxidative stress through BMP4 overexpression, contributing to endothelial dysfunction." (PMID 40469984, 2025). "Together, these results suggested that deficiency of BMP4 in PVAT contributes to endothelial dysfunction." (PMID 36457800, 2022). "Several reports have substantially stated that BMP4 (bone morphogenic protein 4) plays a key role in the development of cardiovascular disease and in causing endothelial dysfunction in humans." (PMID 36359402, 2022). "It is also known that BMP4 activates p38 MAPK in mouse endothelial cells via a ROS-dependent mechanism and that BMP4 causes endothelial dysfunction that can be reversed by a p38 MAPK inhibitor." (PMID 33194000, 2020). "BMP-4 treatment was shown to significantly elevate blood pressure and lead to endothelial dysfunction by increasing the activity of nicotinamide adenine dinucleotide phosphate (NADPH) oxidase in mice." (PMID 36909186, 2023). "Recently, endoglin was shown to aggravate endothelial dysfunction and elevate blood pressure by upregulating BMP-4 expression in mice." (PMID 36909186, 2023). "Especially, the capacity of Ibrutinib to induce endothelial dysfunction can be antagonized by targeting BMP4." (PMID 36145624, 2022). "According to some studies, Bmp4 is a proinflammatory gene that induces endothelial dysfunction and aggravates tissue damage." (PMID 35782573, 2022). "Once more, Wong and colleagues found that BMP-4- or diabetes-mediated endothelial dysfunction was to a certain extent triggered by protein carbonylation reaction." (PMID 36359402, 2022). "The highlighted molecular mechanisms of endothelial dysfunction suggested the role played by BMP4 through binding to platelet-derived growth factors." (PMID 36359402, 2022). "Carotid arteries isolated from BMP4-DKO mice exhibited more severe Ang II-induced endothelial dysfunction compared with that in the controls." (PMID 36457800, 2022). "We demonstrate that in SS rats BMP4 plays a crucial role in HS-induced ENaC activity and endothelial dysfunction via p38 MAPK-dependent activation of Sgk1/Nedd4-2." (PMID 33194000, 2020). "This argument is also supported by a previous study showing that BMP4 is expressed in endothelial cells and can induce endothelial dysfunction." (PMID 33194000, 2020). "A recent study also suggests paeonol attenuates LPS-induced endothelial dysfunction and apoptosis by inhibiting bone morphogenetic protein 4 (BMP4) and TLR4 signaling independently." (PMID 32774428, 2020). "Besides its role as pro-osteogenic signaling inducer, BMP-4 is also related to inflammation and vascular damage, inducing endothelial dysfunction through oxidative stress." (PMID 39697336, 2024). "In addition, increased BMP-4 expression resulted in excessive oxidative stress and endothelial dysfunction in the aortas of diabetic mice." (PMID 36909186, 2023). "Interestingly, hydrogen sulfide was reported to ameliorate endothelial dysfunction in hypertensive rats by inhibiting the BMP-4/COX-2 pathway, which plays a similar role to noggin." (PMID 36909186, 2023). "Besides, in Ang II-induced hypertensive mouse model, BMP4-DKO mice showed further endothelial dysfunction, increased intima-media thickness and collagen deposition." (PMID 36457800, 2022). "Moreover, we identified Ibrutinib as a novel angiogenesis inhibitor via stimulating BMP4 expression leading to vascular endothelial dysfunction." (PMID 36145624, 2022).
endothelial dysfunction (continued). "A pivotal study by Wong and colleagues demonstrated that ROS served as a pathological link between BMP4 stimulation and the downstream cyclooxygenase-2 upregulation in endothelial cells, leading to endothelial dysfunction through ROS-dependent p38 mitogen-activated protein kinase activation." (PMID 36359402, 2022). "Endothelial dysfunction can be ameliorated via inhibiting BMP4 cascade." (PMID 27642495, 2016). "When overexpressed, BMP4 may contribute to endothelial dysfunction, promoting ROS production and apoptosis." (PMID 23755276, 2013). "Notably, adipose tissue BMP4 knockout reduced ACh-induced relaxation in PBS-infused mice, suggesting BMP4 knockout in WAT may contribute to endothelial dysfunction." (PMID 36457800, 2022). "Whether PDGF mediates BMP4-induced endothelial dysfunction in diabetes mellitus." (PMID 36359402, 2022). "Interestingly, endothelial dysfunction precedes and mediates the BMP4-induced hypertensive effect." (PMID 32316263, 2020). "This team further found that BMP-4 overexpression upregulated platelet-derived growth factor AA (PDGF-AA) expression, and both PDGF-AA inhibition and neutralization alleviated BMP-4-induced endothelial dysfunction in diabetes mellitus." (PMID 36909186, 2023). "Next, we performed in vitro angiogenesis assays and found that Ibrutinib was more able to induce endothelial dysfunction than Zanubrutinib via stimulating more BMP4 expression, however, Acalabrutinib had no such effect." (PMID 36145624, 2022).
diabetes (19 papers, 2013 to 2025). "The perivascular region is likely to serve as a target of whitening also in other contexts such as diabetes, which has been associated with enhanced BMP4 expression, potentially affecting the metabolic and thermogenic capacities of BAT." (PMID 38184275, 2024). "Among the highly probable genes involved in the pathogenesis of diabetes in GK rat, it has been demonstrated that the overexpression or inhibition of Fam3b, Ptprn2, Ide, Hnf4g, Bad and Bmp4 is associated with the glucose tolerance in rodents." (PMID 30687391, 2018). "In particular, the mechanism underlying podocyte damage depends on BMP4/BMP receptor signaling in the early stage of diabetes." (PMID 30158674, 2018). "However, the genes Bmp4, Fam3b, and Ptprn2 were found to be associated with diabetes in GK rats for the first time in the present study." (PMID 30687391, 2018). "Beyond IL-4 and IL-10, other members of the TGF superfamily, such as TGF-β3, BMP-2, and BMP-4, are involved in regulating macrophages for bone regeneration in diabetes as well, making them potential targets in future research on biomaterial-based therapy." (PMID 39258053, 2024). "Loaded with BMSCs, RAW264.7 macrophages, and mesoporous silica nanoparticles carrying BMP-4, this scaffold significantly promoted M2 polarization and osteogenic differentiation of BMSCs upon implantation in a diabetic mellitus context." (PMID 39258053, 2024). "To further investigate the expression difference of BMP4, we also collected 32 CRC tissue specimens for qRT-PCR, and the result showed that BMP4 mRNA was upregulated in CRC patients with diabetes." (PMID 37370018, 2023). "Altogether, our data highlight the potential role of the activated BMP4 signaling in regulating retinal endothelial cell dysfunction during diabetes." (PMID 37174679, 2023). "The goal of this study was first to characterize the impact of diabetes on retinal levels of BMP4 and second to investigate the direct effect of BMP4 on retinal endothelial cell barrier function." (PMID 37174679, 2023). "In a mixed model (human/mice) diabetes was induced by means of a generated Ad-Bmp4 to overexpress Bmp4 and Ad-Pdgfa-shRNA to obtain knockdown of Pdgfa in mice." (PMID 36359402, 2022). "BMP4 expression was also much greater in the whole aortas of diabetic ApoE KO mice compared with control mice, suggesting that diabetes also induces aortic BMP4 expression in db/db mice." (PMID 24107300, 2013). "In this study, we found that the mRNA and protein expression levels of BMP, as well as the fibrosis level, were significantly increased in diabetic arterial samples, suggesting that BMP4 might play an important role in aortic fibrosis induced by diabetes." (PMID 41143005, 2025). "The result of our study suggested that BMP4 might serve as a therapeutic target in CRC patients with diabetes." (PMID 37370018, 2023). "However, data from previous clinical experiments reported that serum BMP-4 levels were significantly decreased in patients with diabetes." (PMID 36909186, 2023). "We first examined the development of DN in STZ-induced diabetes models using Bmp4 +/− mice." (PMID 30158674, 2018). "Here, we report for the first time that Fam3b, Ptprn2 and Bmp4 are related to diabetes in GK rats." (PMID 30687391, 2018). "BMP4 is upregulated in db/db mice, an animal model of diabetes." (PMID 24107300, 2013). "The induction of BMP4 in atherosclerotic plaque may promote atherosclerotic plaque formation in diabetes." (PMID 24107300, 2013). "Our finding provides important insights regarding the role of BMP4 as a potential player in retinal endothelial cell dysfunction in diabetic retinopathy and could be a novel target to preserve the blood–retinal barrier during diabetes." (PMID 37174679, 2023). "Altogether, our data propose BMP4 as a novel player that contributes to microvascular dysfunction in DR and could be a new therapeutic target, inhibition of which will mitigate the permeability effect of diabetes in DR." (PMID 37174679, 2023).
diabetes (continued). "Considering that BMP4 may crosstalk glucose metabolism and CRC, we designed this study to investigate whether the increased BMP4 induced by diabetes facilitates the progression of CRC, which may contribute to finding a potential therapeutic target for the treatment of CRC." (PMID 37370018, 2023). "Therefore, the inhibition of the BMP4 cascade may be an avenue to be pursued as a potential additional therapeutic strategy against diabetic vascular dysfunction." (PMID 36359402, 2022). "Persistently high levels of BMP-4 in vascular tissues or serum may be an early sign of diabetes." (PMID 24170999, 2013). "IHC pictures of tumor tissue sections from the flanks of the nude mice demonstrated that diabetes mice upregulated BMP4, Vimentin and N-cadherin expression but downregulated E-cadherin expression compared to the control group, revealing that IR may induce BMP4 to medicate the EMT of CRC." (PMID 37370018, 2023). "BMP4 expression was upregulated in CRC patients, and significantly higher in CRC patients with diabetes (P < 0.05)." (PMID 37370018, 2023). "Both BMP4 and BMP6 have been reported to exert anti-inflammatory effects in human adipocytes and in the context of renal fibrosis in diabetes, respectively." (PMID 29222456, 2017). "In conclusion, the serum levels of BMP-4 and inflammatory markers such as PAI-1 and hsCRP decreased significantly after RYGB in severely obese patients with type 2 diabetes mellitus." (PMID 24170999, 2013). "The results showed that the protein level of BMP4 was higher in patients with diabetes than in patients without diabetes." (PMID 37370018, 2023). "The diabetic model of CRC cell lines in vitro and the mice model in vivo were developed to explore the BMP4 expression during CRC with or without diabetes." (PMID 37370018, 2023). "In animal models of diabetes, BMP-2 and BMP-4 promote vascular calcification." (PMID 36909186, 2023). "For instance, obese individuals who do not have diabetes have elevated levels of bone morphogenetic protein 4 (BMP4)." (PMID 33092038, 2020). "However, no study has investigated the expression difference of BMP4 in CRC with or without T2DM and the underlying mechanism of BMP4 links to CRC and diabetes." (PMID 37370018, 2023). "Our study focused on the effect and underlying mechanism of DM on CRC and our findings indicated opportunities for BMP4 as a novel therapeutic target to reduce metastatic burden in patients and provided evidence that GLP-1RA could be safely used for CRC patients with comorbidity of diabetes." (PMID 37370018, 2023).